IDH1 (isocitrate dehydrogenase (NADP(+)) 1)
Diseases named in the same sentence as IDH1 in open-access papers (continued):
Sharing a sentence is not in itself a finding about the gene and the disease.
glioma (continued). "In lower-grade glioma, DZIP3 expression could predict the survival time in IDH1 mutant and IDH1 wild-type subgroups." (PMID 33229627, 2020). "As for other factors, including the change of sPD-L1, IDH-1 mutational status, tumor position, and Ki-67 expression, none of them exhibits a significant correlation with the PFS of glioma patients." (PMID 33224142, 2020). "In the present study, the MET uptakes in IDH1-wildtype tumours were also significantly higher than that in IDH1-mutant tumours in all gliomas, but this was not the case among grade II and III gliomas." (PMID 32382870, 2020). "Considering the correlation between FTL expression and IDH1/2 or subtypes, use of combination molecular analysis containing FTL might provide a more effective method for predicting prognosis of glioma." (PMID 32677981, 2020). "Irrespective of IDH1 mutation, histogram parameters of Ktransand Ve were correlated with VEGF expression in gliomas (P < 0.05, respectively)." (PMID 33425744, 2020). "This is consistent with the fact that we trained the models based on IDH1 status as opposed to glioma grade." (PMID 33121211, 2020). "IDH1 wild type glioma was mainly found in GBM, but it could be found in the temporal lobe and had a large volume in WHO II glioma." (PMID 32582544, 2020). "To determine whether the oncometabolite (R)-2-hydroxyglutarate (2-HG), which is produced by IDH1 mutant, was responsible for the increased CD73 expression, we cultured PBMCs for 72 hours with 2-HG concentrations typically found in patients with glioma." (PMID 32721947, 2020). "IDH-1, which predicts the prognosis of the gliomas, however, seemed to have no relations with the recurrence modes of the tumors." (PMID 33585189, 2020). "It should be noted that FLT-PET/CT was able to distinguish the IDH1-mutant tumours from wildtype tumours not only in all gliomas, but also in this specific population, but this was not the case for MET-PET/CT." (PMID 32382870, 2020). "IDH1, Ki67, and GFAP were once considered as the golden triad of glioma IHC Ki67 is highly correlated to proliferation that may indicate the tumor grades and prognosis." (PMID 33014836, 2020). "Moreover, the results showed that glioma-related mutant genes included MGMT (n = 14), IDH1 (n = 8), IDH2 (n = 1), 1p/19q (n = 3), and BRAF (n = 2)." (PMID 32973641, 2020). "In addition, AG-881 is a promising orally available dual inhibitor of mutant IDH1 and mutant IDH2 that was in Phase I/II clinical trial until this year, recruiting AML patients with mutant IDH1/2, as well as glioma patients (NCT02492737 and NCT02481154)." (PMID 32548570, 2020). "CNTN1 triggered the activation of endogenous T cells in a substantial proportion for up to 56% of patients with astrocytic and/or oligodendroglial IDH1-mutant lower grade gliomas, but none in healthy donors." (PMID 32752094, 2020). "And although IDH1 and IDH2 mutations are frequent in human gliomas, they are not a consistent or common feature of the canine condition." (PMID 31824863, 2019). "We further investigated the expression of NAD-synthesis enzymes in a very rare cohort of three patient-derived IDH1-mutant glioma cell models that have native homozygous IDH1R132H and additionally five patient-derived glioblastoma cell lines with IDH1-wildtype status." (PMID 31888244, 2019). "D-2HG also inhibits the branched-chain amino acid transaminase 1 (BCAT1) and 2 (BCAT2), which renders IDH1 mutant glioma cells dependent on glutaminase and increases their sensitivity to oxidative stress." (PMID 31450721, 2019). "In one study, D-2HG depletion failed to inhibit the growth of established IDH1 mutant glioma cell lines and tumors, but rendered these tumors exquisitely sensitive to NAMPT inhibition." (PMID 31450721, 2019).
glioma (continued). "Glioma cells harboring a mutant form of isocitrate dehydrogenase (IDH1) exhibited sensitivity to BPTES treatment, which displayed minimal effects on the wildtype IDH1 protein." (PMID 31167399, 2019). "We thus conclude that NAPRT is not involved in NAD+ synthesis in gliomas and therefore its downregulation cannot explain the IDH1-related drop in NAD+." (PMID 31888244, 2019). "Our results suggest that 1H MRS could be useful as a prognostic precision medicine biomarker detection system for identifying, stratifying, and monitoring IDH1 and IDH2 mutant glioma patients." (PMID 30791611, 2019). "AGI-5198 also reduced growth of human IDH1/R132H glioma xenografts in mice and did not impair glioma expressing wild type IDH1, without significant toxicity." (PMID 30857299, 2019). "Overall, regardless of the presence of 1p19q codel, both studies demonstrated that DAC and AZA induce durable therapeutic effects in patient-derived IDH1-mutant gliomas without any signs of tumor re-growth despite termination of administration." (PMID 31652645, 2019). "Preliminary data from a phase I study of patients with IDH1-mut gliomas demonstrated that AG-120 treatment had no dose-limiting toxicity or serious adverse effects." (PMID 30857299, 2019). "Our results suggest that UHF 1H MRS could be useful as a prognostic precision medicine biomarker detection system for identifying, stratifying, and monitoring IDH1 and IDH2 mutant glioma patients towards the goal of precision medicine of gliomas." (PMID 30791611, 2019). "In the case of mutant IDH1 inhibition, the simultaneous decrease of the 2HG/Glx ratio and the increase in ADC might be interpreted as a sign of objective treatment response in glioma patients." (PMID 29662077, 2018). "The dual target inhibitor of mutant IDH1 and mutant IDH2, AG-881, is an orally available inhibitor that can pass the blood-brain barrier and may serve as a better option for glioma patients." (PMID 28748451, 2018). "In is important to note that these studies also showed that proneural glioma stem cells frequently exhibit hypermethylation patterns with similarities to G-CIMP, even in the absence of IDH1 mutations." (PMID 30279357, 2018). "Since IDH1 is part of the tricarboxylic acid (TCA) cycle and plays a major role in energy and oxygen metabolism, it is crucial to understand how hypoxia alters the phenotype of IDHmut glioma cells as compared to its wildtype counterpart." (PMID 30257451, 2018). "In order to confirm that this correlation was not due to the association between grade and IDH1/2 status, we also evaluated TAGLN2 mRNA levels in IDH1/2 WT gliomas of all grades." (PMID 30647847, 2018). "Analysis of the TCGA glioblastoma dataset and the French glioma dataset gse16011, showed no variation in ARNT2 expression according to MGMT status, IDH1 mutation or EGFR amplification (not shown)." (PMID 29149419, 2018). "Thus, it remains to be elucidated how the IDH1/2 mutant-generated oncometabolite, 2-HG, regulates the expression of TAGLN2 and how TAGLN2 in turn drives glioma cell proliferation and invasion." (PMID 30647847, 2018). "A longer survival is observed in patients with gliomas harboring the presence of IDH1 or IDH2 mutations, whereas the absence of IDH1 appears as a strong predictor for poor prognosis." (PMID 29953478, 2018). "This conclusion is strongly supported by the observation that isocitrate dehydrogenase (IDH1 and IDH2) mutations are present in the majority of WHO II and III gliomas and secondary glioblastomas, but not in primary glioblastomas." (PMID 30279357, 2018).
glioma (continued). "In this study, we performed molecular profiling of IDH1/2 WT versus mutant low(er) grade II and III gliomas to identify key molecular pathways that may contribute to differences in survival outcomes." (PMID 30647847, 2018). "Overall, slightly more females (53.2%) as compared to males (47.2%) had IDH1/2 mutant glioma, but this difference was not statistically significant (p = 0.1104)." (PMID 29743610, 2018). "In addition to IDH1, the methylation status of the MGMT promoter is routinely assessed in glioma patients." (PMID 30534602, 2018). "Gliomas harbouring IDH1 mutations belong to the group of WHO grade II and III gliomas typically lacking vascular proliferations or account for only approximately 5% of secondary glioblastomas." (PMID 29844871, 2018). "In contrast, IDH-1-mutant (R132H) glioblastomas mainly present as secondary glioblastoma deriving from lower grade gliomas that – per definition – do not display vascular proliferations." (PMID 29844871, 2018). "Mutant IDH1 was statistically significantly related to both higher G0S2 methylation (0.749 vs. 0.366, p = 9.439e-53) and lower G0S2 expression (3.1 vs. 7.03, p = 0.000) compared to wild-type IDH1 among WHO grade II–IV gliomas." (PMID 30388142, 2018). "His research team also used perfusion and diffusion MRI signatures to successfully stratify lower grade glioma into three subpopulations as IDH1 mut/1p19q codel, IDH1 mut/1p19q non-condel and IDH1 wt." (PMID 28915860, 2017). "In this prospective study using 7 Tesla MRI, we found significantly higher SWI-LIV values in HGG compared to LGG, IDH1-R132H negative compared to IDH1-R132H positive gliomas and tumours with significant CE compared to non-significant CE on MRI." (PMID 27300198, 2017). "Clinical information regarding the progression of the single case of glioblastoma in this study with identified mutant IDH1 staining signal was not available, but histopathological evidence of lower grade glioma involvement was observed." (PMID 31548536, 2017). "The results showed that 2-HG was detected in the IDH1-mutant gliomas but was absent in IDH1 wild-type gliomas." (PMID 28710497, 2017). "Therefore, 2HG can be used as a specific Magnetic Resonance Biomarker, monitoring IDH1 and IDH2, tracking glioma state and identifying the boundary between tumor and normal tissue." (PMID 28939851, 2017). "In contrast, expression levels of enzymes involved in downstream metabolism of isocitrate, including IDH1, IDH2 and IDH3A, α-KGDH, succinate dehydrogenase (SDHB), fumarate hydratase (FH) and malate dehydrogenase (MDH2), were remarkably lower in IDH1MUT glioma versus IDH1WT glioma." (PMID 28467784, 2017). "Existing reports showed that chemokine network could promote the invasiveness and angiogenesis of glioma cells; the chemokine receptor CXCR7 contributed to glioma's invasion and angiogenesis, and its expression related to poor outcome in IDH1 mutant patients." (PMID 29221210, 2017). "The last meta‐analysis published of 55 observational studies and 9487 patients with gliomas showed a significant OS and PFS advantage for patients with IDH1/2 mutations over those without them." (PMID 28948065, 2017). "For example, another clinical trial based on the mutant isocitrate dehydrogenase type 1 (IDH1) for recurrent grade II astrocytoma (NCT02193347) has shown greater efficacy; the mutant IDH1 is carried by more than 70% of diffuse grade II and III gliomas." (PMID 28299344, 2017). "One current shortcoming is that SWI-LIV values can be increased in case of a HGG or an IDH1-R132H negative glioma and thus the SWI-LIV technique alone cannot differentiate between these two aspects." (PMID 27300198, 2017).
glioma (continued). "The GB10 model, a novel IDH1 R132H mutant glioma intracranial model, was developed to test if the observed BT142 survival benefit could be seen in other mutant glioma models." (PMID 29062039, 2017). "For example, IDH-1 is prognostically favorable among gliomas but is almost entirely absent from elderly GBM." (PMID 28775928, 2017). "Conversely, expression of GLUD2 (but not GLUD1) promotes tumor expansion, suggesting that R132H IDH1 glioma cells proliferate by utilizing enhanced glutamate flux through the GLUD2 pathway." (PMID 28208702, 2017). "Here, we applied in situ metabolic profiling and LC‐MS on brain sections of glioma PDX and human glioma samples with and without the IDH1 mutation for large‐scale unbiased metabolic profiling of these tumors." (PMID 29054837, 2017). "MGMT promoter methylation and consequently low MGMT expression is typical in, but not unique to IDH1 mutant gliomas, which generally respond better to TMZ than their IDH1 wild type (WT) counterparts." (PMID 28178660, 2017). "It is intriguing to speculate that stronger expression of IDH1 R132H, as seen in BT142, may predict tumor response in low grade glioma patients, but this hypothesis requires additional preclinical and/or clinical validation." (PMID 29062039, 2017). "Our results suggest that they may have antiproliferative activity in IDH1 mutant cancers, including AML, glioma, secondary glioblastoma and osteosarcoma." (PMID 28561042, 2017). "The resulting three categories were as follows: I-A (IDH1/ATRX mutation), I-CF (IDH1/CIC/FUBP1 mutation), and I-X gliomas (not I-A or I-CF)." (PMID 29026176, 2017). "Lower-grade gliomas (LGGs, grades II and III) and glioblastomas (grade IV) have been redefined by the presence or absence of the IDH1/2 mutation." (PMID 28698530, 2017). "Furthermore, the transcriptional impact of 2-HG on PTP expression in IDH1 wildtype glioblastoma cells was at best opposite to the expected, and not able to tone down PTP mRNA levels to those in lower grade gliomas or normal brain tissue." (PMID 27586084, 2016). "Now, we used negative IDH1-R132H combined with higher Ki-67 expression to define the cluster similar to the IDH-wt/TERTp-mut gliomas." (PMID 27713914, 2016). "In addition, our cohort contained a larger sample size, thus, we assessed the diagnosis value IDH1-R132H and (or) ATRX status for human gliomas and observed that the progressive pattern of gliomas based on the precious cohort." (PMID 26918938, 2016). "We found that hyperpolarized [1-13C]-lactate produced from hyperpolarized [1-13C]-pyruvate was comparable between mutant IDH1 tumors and normal brain in the BT142 model, in contrast to wild-type IDH1 glioma models, wherein hyperpolarized [1-13C]-lactate is significantly higher than in normal brain." (PMID 27014635, 2016). "Understanding the underlying biology of the differences in outcome observed for IDH1 and IDH2 mutant gliomas will be important for future studies and may lead to the development of novel approaches to therapy." (PMID 27245697, 2016). "Our aim was to provide insight into the differences between IDH1 and IDH2 mutant gliomas." (PMID 27245697, 2016). "In addition, whole-transcriptome sequencing and DNA methylation data were used to assess the distribution of genetic changes in IDH1 and IDH2 mutant gliomas in a Chinese population-based cohort." (PMID 27245697, 2016). "Finally analysis of low-grade glioma patient biopsy data from The Cancer Genome Atlas revealed that MCT1 and MCT4 expression was significantly reduced in mutant IDH1 tumors compared to wild-type." (PMID 27144334, 2016). "IDH1-R132H and ATRX expression status are essential to the diagnosis for gliomas." (PMID 26918938, 2016). "Based on these previous reports, the expectation is that congenital gliomas (including congenital oligodendroglioma) would similarly be negative for the mutant specific IDH1 immunohistochemical stain, as was exhibited in the current case." (PMID 25755903, 2015).
glioma (continued). "The authors demonstrated the existence of a genomic group of IDH1/2 wild-type lower-grade gliomas (Group IV) lacking glioblastoma-like genomic aberrations such as 7q gains and 10q losses." (PMID 26369702, 2015). "Mutant IDH1 and IDH2 alter glioma metabolism, favoring the reduction of α-ketoglutarate to 2-hydroxyglutarate (2-HG), which in turn inhibits DNA and histone demethylases and establishes a glioma-CpG island hypermethylator phenotype (G-CIMP), featuring hypermethylation at a large number of loci." (PMID 25785247, 2015). "IMP3 expression was significantly associated with the absence of mutations of IDH1 gene (P = 0.0001) and with the unmethylated phenotype of MGMT in high-grade gliomas (P = 0.004)." (PMID 25695077, 2015). "IDH1 and IDH2 genes have become a focus for research aimed at understanding the biology of gliomas." (PMID 26220714, 2015). "Non-treated IDH1 mutant glioma cells produce an excess of 2-HG relative to wild type glioma cells (7.8 fold; p < 0.001); 2-HG levels increased further after 5-ALA treatment (1.7 fold; p < 0.005)." (PMID 26008980, 2015). "Our results suggested not all IDH1/2 wild-type lower-grade gliomas are aggressive and additional biomarkers are required to identify glioblastoma-equivalent tumors." (PMID 26369702, 2015). "In regards to clinical features of gliomas, V-ATPase G1 was more expressed by tumors wild-type for IDH1 enzyme whereas it did not correlate to MGMT promoter methylation." (PMID 26020805, 2015). "Our analyses of TMA-based glioma patient cohort as well as TCGA glioma dataset consistently indicate that the expression of CD151 or α3β1 integrin is strongly correlated with tumor grade, IDH1 gene status, and patient survival." (PMID 26377974, 2015). "In the present study, the heme biosynthesis pathway lags in IDH1 mutant malignant gliomas; 5-ALA overload due to insufficient NADPH can result in a temporary difference in PpIX accumulation relative to wild type IDH1 malignant glioma cells." (PMID 26008980, 2015). "MGMT promoter methylation is a common feature of IDH1/2 mutant/G-CIMP positive glioma, however, is less prevalent in G-CIMP negative tumors, such as primary glioblastoma, where MGMT methylation occurs in approximately 40% of cases." (PMID 25785247, 2015). "In regarding pediatric gliomas, apart from a single recurrent pilocytic astrocytoma and a primary glioblastoma which were IDH1 positive, all others were IDH1 negative." (PMID 27275230, 2015). "Curiously, although IDH1 and IDH2 mutations are clearly powerful drivers of low grade glioma and AML, they seem to be rare or absent in other tumor types." (PMID 25232952, 2014). "PDGFRA amplification has recently been shown to be associated with a poor prognosis in IDH1 mutant GBM and have a negative prognostic value in Grade III gliomas." (PMID 24716189, 2014). "Mutant forms of metabolic enzyme isocitrate dehydrogenase (IDH1) are found in a great proportion of secondary gliomas, but are absent in the primary glioblastomas." (PMID 23516171, 2013). "In our initial studies, we have not observed sensitization of IDH1-mutant glioma cells to IDH1 R132H specific inhibitor, AGI-5198 following DAC exposure; however, further studies are needed." (PMID 24077826, 2013). "Transient exposure to nanomolar concentrations of DAC induces the differentiation of the IDH1 R132H, but not IDH1 wild-type glioma-initiating cells." (PMID 24077826, 2013). "Blockade of mutant IDH1 impaired the growth of glioma cells possessing mutant IDH1, but not that of IDH1 WT glioma cells without appreciable changes in genome-wide DNA methylation." (PMID 24403254, 2013). "The specificity of staining was validated using 10 gliomas with sequence proven IDH1 R132H and 5 IDH1 wildtype tumors (data not shown)." (PMID 22829908, 2012). "We and others have previously reported loss of heterozygosity at the IDH1 locus in gliomas and leukemias, and monoallelic expression of IDH1 in gliomas is not uncommon." (PMID 23267435, 2012).